ZCCHC24 (zinc finger CCHC-type containing 24)
Synonyms: C10orf56; FLJ90798; Z3CXXC8
Tractability: PROTAC: ubiquitination databases record sites on it.
Gene: Protein-coding gene on chromosome 10 (79,382,325 to 79,445,625, reverse strand). Ensembl gene ENSG00000165424.
Subcellular location (Human Protein Atlas): Mitochondria; Nucleoplasm
Gene Ontology:
Molecular function: RNA binding; nucleic acid binding; zinc ion binding
Genetic constraint (gnomAD): Loss-of-function variants: 10 observed, 21.09 expected, observed/expected ratio (o/e) 0.47, 90% interval 0.29 to 0.8. The upper end of that interval is the gene's LOEUF score, 0.8, which puts it in group 3 of 6, group 1 being the genes least tolerant of losing a copy. Missense variants: 243 observed, 280.7 expected, observed/expected ratio (o/e) 0.87, 90% interval 0.78 to 0.96. Synonymous variants: 144 observed, 122.85 expected, observed/expected ratio (o/e) 1.17, 90% interval 1.02 to 1.35.
Homologues: Orthologues: chimpanzee ZCCHC24 (100% identical), macaque ZCCHC24 (100% identical), pig ZCCHC24 (98% identical), mouse Zcchc24 (98% identical), rabbit ZCCHC24 (98% identical), tropical clawed frog zcchc24 (87% identical), zebrafish zcchc24 (86% identical), guinea pig ZCCHC24 (79% identical), rat Zcchc24 (70% identical), Caenorhabditis elegans Y43E12A.2 (37% identical). Paralogues in human: RBBP6 (27% identical).
Diseases named in the same sentence as ZCCHC24 in open-access papers:
ZCCHC24 is named in the same sentence as 7 diseases in open-access papers, as found by Europe PMC text mining. Sharing a sentence is not in itself a finding about the gene and the disease. The quoted sentences say what the papers report.
breast carcinoma (2 papers, 2019 to 2020). "Previous studies have reported that several genes, such as NTHL1, ZCCHC24, and SNX1b, have different methylation status in different subtypes of breast cancer." (PMID 32633782, 2020). "Therefore, the expression pattern of ZCCHC24 in different breast cancer subtypes may be functionally different, and its specific methylation pattern affecting its expression level may also be different and discriminative." (PMID 31480430, 2019). "In addition to ZCCHC24, another zinc finger protein coding gene named ZNF282 has also been predicted as a potential distinctive marker for different breast cancer subtypes." (PMID 31480430, 2019).
bladder tumor (1 paper, 2022). "The expression levels of a portion of feature genes, such as ANGPTL2, CAV1, FNBP1, FXD6, MAP1A, and ZCCHC24 were significantly decreased in bladder tumor cell lines." (PMID 35719407, 2022).
Breast Invasive Carcinoma (1 paper, 2024). "Supporting these results, the RNA expression levels of ZEB1 and ZCCHC24 in the Cancer Genome Atlas Breast Invasive Carcinoma (TCGA-BRCA) dataset (1178 samples) were strongly correlated." (PMID 39420119, 2024).
stomach cancer (1 paper, 2023). "ZCCHC24 is a gene known to bind to RNA and regulate RNA splicing, also correlated with immune cell infiltration in lung and stomach cancer, whose expression levels significantly correlated with poor survival." (PMID 37091785, 2023).
triple-negative breast carcinoma (1 paper, 2024). An invasive breast carcinoma which is negative for expression of estrogen receptor (ER), progesterone receptor (PR), and human epidermal growth factor receptor 2 (HER2). "RNA binding protein ZCCHC24 promotes tumorigenicity and forms a positive feedback loop with the transcription factor ZEB1 in triple negative breast cancer (TNBC)." (PMID 39420119, 2024).
cancer (5 papers, 2019 to 2024). A tumor composed of atypical neoplastic, often pleomorphic cells that invade other tissues. "One of the ZCCHC24 targets, ZEB1, is a transcription factor that promotes the expression of cancer stemness genes and reciprocally induces ZCCHC24 expression." (PMID 39420119, 2024). "We evaluated the role of ZCCHC24 in tumorigenicity in vivo by subcutaneously transplanting cancer cells diluted with siRNAs targeting ZCCHC24." (PMID 39420119, 2024). "Notably, the function of ZCCHC24 has not been well characterized, and its function in cancer remains unknown." (PMID 39420119, 2024).
tumor (3 papers, 2019 to 2024). "The therapeutic efficacy of targeting ZCCHC24 was demonstrated by a significant and specific reduction in the mesenchymal-like population when ZCCHC24-knockdown cells were transplanted into tumor tissue." (PMID 39420119, 2024). "ZCCHC24 knockdown also has additive effects with the BET inhibitor JQ1 in suppressing tumor growth in TNBC patient-derived xenografts." (PMID 39420119, 2024). "We also performed extremely limited dilution analysis (ELDA) in vitro with MDAMB231, HCC38, and PDX cells and found that ZCCHC24 knockdown decreased their tumor-forming abilities (Fig. EV4B–D)." (PMID 39420119, 2024). "In this context, we anticipate that ZCCHC24 will stabilize mRNAs that characterize tumor initiation and treatment resistance by counteracting some of the target mRNAs in Pumilio." (PMID 39420119, 2024). "From miRNAs, miR-200 was highly upregulated with its targets down in tumour samples, namely, ZCCHC24 with survival significance found." (PMID 37091785, 2023). "To test this in vivo, we added siRNAs against ZCCHC24 together with JQ1 treatment to subcutaneously grafted MDAMB231 or PDX cells and found that the dual use of JQ1 and siRNA against ZCCHC24 had additive effects in suppressing tumor growth in both models compared with single treatments." (PMID 39420119, 2024).